HEPN1 (hepatocellular carcinoma, down-regulated 1)
Tractability: No criterion of Open Targets' tractability assessment is met for any kind of drug.
Gene: Protein-coding gene on chromosome 11 (124,919,250 to 124,920,677, forward strand). Ensembl gene ENSG00000221932.
Subcellular location: Cytoplasm
Subcellular location (Human Protein Atlas): Golgi apparatus
Gene Ontology:
Cellular component: cytoplasm
Genetic constraint (gnomAD): Loss-of-function variants: 0 observed, 0.29 expected, observed/expected ratio (o/e) 0, 90% interval 0 to 1.87. That is too few expected variants to judge how well the gene tolerates losing a copy. Missense variants: 97 observed, 107.6 expected, observed/expected ratio (o/e) 0.9, 90% interval 0.76 to 1.07. Synonymous variants: 44 observed, 42.53 expected, observed/expected ratio (o/e) 1.03, 90% interval 0.81 to 1.33.
Homologues: Orthologues: chimpanzee HEPN1 (98% identical).
Diseases named in the same sentence as HEPN1 in open-access papers:
HEPN1 is named in the same sentence as 3 diseases in open-access papers, as found by Europe PMC text mining. Sharing a sentence is not in itself a finding about the gene and the disease. The quoted sentences say what the papers report.
hepatocellular carcinoma (3 papers, 2011 to 2018). A malignant tumor that arises from hepatocytes. "Another gene that we found up-regulated by RORα is HEPN1, which encodes a peptide involved in the control of cell growth and apoptosis, and whose expression is down-regulated in hepatocellular carcinoma." (PMID 21818335, 2011). "Hepatocellular carcinoma, downregulated 1 (HEPN-1) gene is a novel tumor suppressor gene first described in human hepatocellular carcinoma (HCC)." (PMID 32922863, 2018). "Among them, we found HEPN1, a tumor suppressor in hepatocellular carcinoma and pituitary somatotroph adenomas based on genetic evidence." (PMID 26573612, 2015).
glioma (1 paper, 2024). A benign or malignant brain and spinal cord tumor that arises from glial cells (astrocytes, oligodendrocytes, ependymal cells). "Furthermore, we could identify several novel glioma biomarkers likely helpful in both diagnosis and prognosis of the patients, including the genes PPP1R8, GPBP1L1, KIAA1614, C14orf23, CCDC77, BVES, EXD3, CD300A, and HEPN1." (PMID 38812741, 2024).
tumor (1 paper, 2015). "Among the functional human orthologs of these minipig pseudogenes we found HEPN1, a putative tumor suppressor gene." (PMID 26573612, 2015).